PRDX3 (peroxiredoxin 3)
Diseases named in the same sentence as PRDX3 in open-access papers (continued):
Sharing a sentence is not in itself a finding about the gene and the disease.
cancer (continued). "Our survey of studies analyzing the involvement of mitochondrial Prdxs in human cancers shows that most of the conducted studies are based on the expression analysis of Prdx3 and Prdx5." (PMID 31500275, 2019). "This difference between Prdx3 and miR-383 relationship in MB cells and MB samples implies the need for in-vivo studies to further enhance the understanding of Prdx3 roles in cancer cell survival and metastasis." (PMID 31500275, 2019). "The expression of Prdx3 is upregulated in the endometrium of patients that suffer from this type of cancer as compared to that in normal endometrium." (PMID 31500275, 2019). "The signaling and regulation of Prdx3 varies, depending on the type of cancer and its interacting partners." (PMID 31500275, 2019). "FOXM1 is associated with cancer cell proliferation and the FOXM1/Prdx3 pathway plays a role in the survival of cells, so they can be specifically targeted to develop the efficient drugs." (PMID 31500275, 2019). "PRDX3, which is predominantly localized in mitochondria and up-regulated in several human cancers, seems to confer increased treatment resistance and aggressive phenotypes." (PMID 27966448, 2017). "Overexpression of PRDX2 and PRDX3 has been reported in many kinds of cancer though it’s low or even undetectable in normal tissues." (PMID 28184180, 2017). "The expression suppression of mitochondrial PRDX3 protein in the anti-oxidative stress system enhanced the mobility potential of NPC metastatic cancer cells, which consolidates the roles of mitochondrial oxidative stress in NPC metastasis." (PMID 23217164, 2012). "This might be indicative of a systemic reduction in mitochondrial activity in carcinoma patients, consistent with the potential loss of PGC-1α activation capacity and altered PRDX3/PFKFB3 correlation." (PMID 37047426, 2023). "Like Prdx3, the up- and downregulation of Prdx5 is also observed in many types of cancers." (PMID 31500275, 2019). "Some of the transcription factors that were specifically expressed in OS-DW cells were ATF6, CDX2, FOSL1, PRDX3, FZD6, MYNN, TRAF1 which are known to regulate pathways implicated in cancers like, Wnt/Hedgehog/Notch signaling, MAPK signaling, Apoptosis and mTOR signaling." (PMID 31690262, 2019). "This study is significant in that both in vitro and in vivo results showed that Prdx3 is regulating the survival and metastasis of cancer stem cells through mitochondrial stabilization and the depletion of Prdx3 can lead to reduce tumor size and promote cell death by mitochondrial dysfunctions." (PMID 31500275, 2019). "Hence, Prdx3 can be considered as pro-cell survival, either in healthy or diseased cells, and it can be targeted for cancer treatment." (PMID 31500275, 2019). "Peroxiredoxin 3 (PRX3) is a mitochondrial antioxidant that regulates apoptosis in various cancers." (PMID 28240739, 2017). "Since most chemotherapy or radiotherapy for cancer works through an ROS increase and apoptotic induction, our results provide a clue that PRDX3 may be involved in therapy resistance in LSCC." (PMID 27966448, 2017). "Among these proteins, six are reportedly related to cell survival and death; i.e., RhoGDI, GRP78, TXNDC5, COMD9, EIF4E, and PRDX3, which reportedly affect Rho GTPase activity, ER stress, cancer progression, NF-κB suppression, cell growth, cell cycle progression, and apoptosis." (PMID 27428937, 2016). "The class of verified anti-apoptotic molecules overexpressed in cancer includes prominent tumor-associated proteins such as β-Catenin (CTNNB1), Osteopontin (OPN/SPP1), BMI1, Peroxiredoxin 3 (PRDX3;) and DAD1." (PMID 23717670, 2013). "Furthermore, several studies have demonstrated that the overexpression of PRDX1, PRDX2, and PRDX3 has an important role in many cases of drug resistance and that the therapeutic agents targeting these PRDXs are frequently studied for the treatment of cancer." (PMID 27418953, 2016).
cancer (continued). "Peroxiredoxin 3 (PRDX3), a mitochondrial hydrogen peroxide scavenger, is known to be upregulated during tumorigenesis and cancer progression." (PMID 38321552, 2024). "We found a significant difference for the PFKFB3/PRDX3 correlation, with PFKFB3/PRDX3 values higher in the carcinoma group." (PMID 37047426, 2023). "We also observed a significant difference in the PRDX3/PFKFB3 correlation at the gene expression level, between carcinoma and hyperplasia patients, also indicative of increased systemic metabolic stress in cancer patients." (PMID 37047426, 2023). "Specifically, the observed co-regulation of PRDX3 and PRDX4 has been proposed as an outcome of antioxidant response and oxidative damage in cancer." (PMID 29433420, 2018). "A recent study further suggests that Prdx3 is an indispensable scavenger of ROS that protects HCC cells against ROS-induced damage and subsequent apoptosis, allowing favourable conditions for cancer cell proliferation and chemoresistance." (PMID 28994702, 2017). "While PRDX3, PRDX4, and PRDX6 play a tumor-promoting role in the progression of many cancers, PRDX5, similar to PRDX1, has an antitumor effect in breast cancer development." (PMID 27418953, 2016). "Only two of the genes - PRDX3 and RPS19, were notable with a FDR≤0.2 comparing CIN3/cancers to random controls." (PMID 22496757, 2012). "Additionally, the overexpression of peroxiredoxin 3 (PRDX3) regulates mitochondrial ROS, protecting cancer cells from oxidative stress." (PMID 40110186, 2025). "Furthermore, PRDX3 overexpression also induced phosphorylation of MAPK and other serine/threonine kinases, which are important in cancer metastasis." (PMID 38321552, 2024). "Notably, PRDX3 expression was positively correlated with MMP-1 expression in both epithelial (Spearman’s rho = 0.2868, P < 0.001) and stromal parts (Spearman’s rho 0.2205, P < 0.01) of cancer tissues." (PMID 38321552, 2024). "Many nutraceuticals and antioxidants, such as vitamin C, selenium, and lycopene, have been developed for cancer prevention and treatment as they can scavenge ROS; likewise, AZA can exert antileukemic effects by decreasing ROS levels via upregulation of Prdx2 and Prdx3." (PMID 33425206, 2020). "Importantly, none of SNPs associated with the two genes of interest (PRDX3 and RPS19) were statistically significantly different between CIN3 and cancers." (PMID 22496757, 2012).
tumor (44 papers, 2011 to 2026). "PRDX3 levels were significantly associated with patient prognosis in multiple tumor types, suggesting context-dependent roles in tumor biology." (PMID 41838687, 2026). "The expression of Prdx3 and Prdx5 in different types of malignancies involves their association with different factors, such as transcription factors, micro RNAs, tumor suppressors, response elements, and oncogenic genes." (PMID 31500275, 2019). "It is clear that Prdx3 is regulated by multiple factors and there is a dire need to analyze the co-relational regulation of Prdx3 by transcriptional factors and micro RNAs to identify the associated changes on the tumor microenvironment." (PMID 31500275, 2019). "Since PRDX3 expression in LSCC was associated with cell differentiation and tumor depth, the possible biological significance of PRDX3 in tumorigenesis was investigated through loss-of-function studies in vitro." (PMID 27966448, 2017). "Collectively, our results support PRDX3 as potential prognostic biomarker and suggest a tumor-suppressive role in KIRC, although further mechanistic and in vivo validation is warranted." (PMID 41838687, 2026). "In a recent study on colorectal cancer, PRDX3 inhibition sensitized CSCs to 5-fluorouracil (5-FU), resulting in a significant reduction in tumor growth." (PMID 40608151, 2025). "In our study, we silenced PRDX3 in detached CCa cells and detected an increase in intracellular ROS and mitochondrial ROS accompanied by a higher proportion of tumor cell apoptosis." (PMID 41049446, 2025). "Subsequently, a logistic regression model was carried out to further evaluate the feasibility of the combination of LVSI, tumor size, and PRDX3 expression to predict LNM in CCa." (PMID 41049446, 2025). "Small-molecule inhibitors targeting PRDX3 have demonstrated potential in preclinical models, leading to increased ROS-induced cell death and reduced tumor burden." (PMID 40608151, 2025). "Proteomic or transcriptomic analyses are required to further understand how PRDX3 contribute to the tumor progression." (PMID 38321552, 2024). "On the contrary, PRDX2 and PRDX3 showed higher expression levels in C4 subtypes, indicating that they are involved in tumor suppression." (PMID 34246267, 2021). "While PRDX3 down-regulation was associated with increasing tumor stage, S100A9 and PHB increased in abundance and were also associated with tumor grade." (PMID 32742246, 2020). "PRDX3 was significantly up-regulated in tumor tissues of LSCC compared with normal adjacent tissues." (PMID 27966448, 2017). "The results showed that up-regulated expression of PRDX3 was observed in LSCC and associated with poor differentiation (P < 0.01), primary tumor location, N category and tumor stage (P < 0.05)." (PMID 27966448, 2017). "We found a significant difference in PRDX3 expression according to N category, tumor stage, and histological grade (p<0.05)." (PMID 27966448, 2017). "The proteomic clusters included tumor upregulated (PRDX3, APOA1, CLIC1) and downregulated (NFM, NDUS1, MDHC, ALDOC, STMN1, PEBP1, DDAH1, CN37) proteins." (PMID 25050814, 2014). "The expression levels of miR-23b and PRDX3 in PCa tissues were found to be related to the severity of the tumor malignancy, suggesting their clinical relevance." (PMID 24191917, 2013). "Unexpectedly, 9 genes showed the inverse association, including the tumor suppressor genes: RUNX1, CBX7, PRDX2 and PRDX3." (PMID 23077491, 2012). "In contrast to the strong PRDX3 expression in the control a continuous stage-dependent decrease was observed in tumor samples." (PMID 21760917, 2011). "Considering only the tumor samples, the immunohistochemical estimation of PRDX3 revealed a maximum at pT2 as well as in G2 tumors." (PMID 21760917, 2011). "Functional analyses indicated that PRDX3 may affect tumor progression through programs related to cell-cycle regulation, metabolism, and redox processes." (PMID 41838687, 2026).
tumor (continued). "In summary, we have elucidated a new PRDX3-mediated mechanism of LNM in CCa, where PRDX3 could promote tumor cell invasion, lymphangiogenesis and LNM via NF-κB signaling pathway and scavenging ROS level to resist anoikis." (PMID 41049446, 2025). "Moreover, PRDX3 promotes primary tumor cell invasion, lymphangiogenesis and LNM in CCa via NF-κB signaling pathway." (PMID 41049446, 2025). "Furthermore, we constructed ROC curves of these three markers, assessing the discriminatory power of LVSI, tumor size, and PRDX3 expression to predict LNM in CCa." (PMID 41049446, 2025). "To further investigate whether PRDX3 is an independent risk factor for LNM in CCa, we conducted multivariate logistic regression analysis and found that all of LVSI, tumor size and PRDX3 expression possess independent predictive power for LNM in CCa." (PMID 41049446, 2025). "MiR-383 operates as a tumor suppressor in MB, in part by targeting PRDX3." (PMID 36313570, 2022). "mRNA content for mitochondrial genes were not different between groups; however, mitochondrial proteins MnSOD, Prdx3, and CoxIV were decreased by ~20–50% in WT and Sod1KO tumour‐bearing mice when compared with WT saline and Sod1KO saline mice, respectively (P = 0.02–0.049)." (PMID 32918528, 2020). "All PRDX proteins were found to be expressed in LSCC tumors and adjacent normal tissues, but PRDX3 was significantly up-regulated in tumor tissues, indicating that it may serve as a promising tumorigenesis-associated protein." (PMID 27966448, 2017). "We also found a difference of PRDX3 expression in primary tumor location." (PMID 27966448, 2017). "PRDX3 is located in mitochondria and guards emergent tumor cells against apoptosis." (PMID 24967385, 2014). "In addition, we found that thiostrepton, a PRDX3 inhibitor, can synergize with chemotherapy to suppress tumor growth in SCLC, suggesting that thiostrepton might be a promising new tool for overcoming SCLC chemoresistance." (PMID 41764940, 2026). "One of the selected proteins via Biomarker Filter IPA was the mitochondrial matrix protein peroxiredoxin 3 (PRX3; Uniprot ID: P30048), which was strongly (8-fold) and frequently elevated in PDAC and had the potential to be secreted from tumor tissue." (PMID 40647510, 2025). "The results indicated that PRDX3 was significantly correlated with FIGO stage (P = 0.001), tumor size (P < 0.001), LNM (P < 0.001), and lymphovascular space invasion (LVSI) (P = 0.042) in CCa." (PMID 41049446, 2025). "The results revealed high PRDX3 expression in all PCa tumor cell clusters, whereas SPHK1 expression was much lower in both PCa and mHSPC samples, indicating a high abundance of PRDX3 in PCa cells." (PMID 40849495, 2025). "Then we explored the relationship between PRDXs and tumor stage and found that only PRDX2, PRDX3, and PRDX4 were significantly correlated with COAD stage." (PMID 36969053, 2023). "Other tumor suppressor genes such as FOXO transcription factors, function by activating many antioxidant genes, such as Prdx3 and Prdx5." (PMID 31500275, 2019). "Building on our network result that key gene set 2 is enriched for mitochondrial energy metabolism, the late-stage regulators we identified—UQCR11, NDUFB4, PRDX3, and S100A10—map to pathways that could support or amplify ADSCs-to-tumor bioenergetic coupling." (PMID 41325391, 2025). "Excessive ROS production by T15 treatment activates different counter mechanisms trying to partially protect the tumor cells against oxidative stress, such as the higher expression of NOX1 on MCF7 cells; PARK7, PRDX1 and PRDX3 on MDA-MB231 cells; and UCP1 elevation in PANC1 cells." (PMID 41011284, 2025). "All PRDXs were highly expressed in BLCA tumor tissues compared with normal tissues, though there is no significant different in expression levels of PRDX2, PRDX3 between tumor and normal tissues." (PMID 34246267, 2021).
tumor (continued). "Tumor cells must adapt in order to evade this fate and therefore commonly over-express antioxidant enzymes, such as superoxide dismutase 2 (MnSOD, SOD2) and peroxiredoxin 3 (PRX3), which permits escape from oncogene-induced senescence." (PMID 25462069, 2014). "Network 3 was characterised by the insertion of a hub protein HNF4alpha, a transcription factor recently shown to play a role in other neoplasias and Network 4 was characterised by numerous mitochondrial-localised proteins (CAT, IDH3A, NDUFS3 and other complex 1 proteins, OXCT1 and PRDX3)." (PMID 24838487, 2014). "For DDAH1, ARGI2, eIF4A3, PRDX3 and Par4 results have not shown significant changes in their respective mRNA levels in tumor compared to benign tissues (Data not shown)." (PMID 21347291, 2011). "Loss of oxidative phenotype (SDH stain) and mitochondrial content (Prdx3, MnSOD, and CoxIV) occurs in WT tumour‐bearing mice, but not tumour‐bearing Sod1KO mice, which may contribute to the loss of respiratory capacity in tumour‐bearing mice." (PMID 32918528, 2020). "In the present study we could demonstrate a significant stage-related downregulation of PRDX3 in tumor cells compared to non-neoplastic tissue." (PMID 21760917, 2011). "However, no expressional significance of PRDX3 (p=0.150) and PRDX5 (p=0.322) was shown, consistent with their expressional differences between all the tumor samples and the normal controls in TCGA-COAD dataset via TIMER, indicating the reliability of the paired samples T tests." (PMID 32231717, 2020).
infection (4 papers, 2013 to 2025). The state of being infected such as from the introduction of a foreign agent such as serum, vaccine, antigenic substance or organism. "The mRNA expression level of PRDX3 gradually increased after infection, peaked at 6 weeks, and then gradually decreased (F = 12.53, P < 0.05) and was negatively correlated with the miR-383-5p level." (PMID 40462224, 2025).
adenocarcinoma (1 paper, 2020). A common cancer characterized by the presence of malignant glandular cells. "However, only PRDX2, PRDX3, and PRDX6 expression was associated with worse OS in adenocarcinoma patients." (PMID 32908916, 2020). "Moreover, PRDX2 and PRDX6 exhibited stronger connections than PRDX3 in adenocarcinoma patients." (PMID 32908916, 2020).
PRDX3 also shares sentences with these, for which no sentence is quoted: ischemia (3 papers); renal cell carcinoma (3); cardiovascular disease (2); cerebellar ataxia (2); mesothelioma (2); neuroblastoma (2); Parkinson's (2); prostate tumor (2); thyroid cancer (2); Ureteral obstruction (2); viral infections (2); acute kidney injury (1); acute promyelocytic leukemia (1); Arthritis (1); asthma (1); autosomal recessive spinocerebellar ataxia (1); bladder cancer (1); cardiac disease (1); cholestasis (1); chronic hepatitis (1); Cirrhosis (1); COVID-19 (1); dengue (1); developmental delay (1); dilated cardiomyopathy (1); Down syndrome (1); dysferlinopathy (1); Dystonia (1); endotoxemia (1); esophageal cancer (1).
A further 28 diseases each share a sentence with PRDX3 in 1 paper.